TNF (tumor necrosis factor)
Diseases named in the same sentence as TNF in open-access papers (continued):
Sharing a sentence is not in itself a finding about the gene and the disease.
melanoma (continued). "In vitro: the use of phenolic compounds, apigenin and/or quercetin, can inhibit the TNF-α-induced VCAM-1 expression and decrease the adhesion of melanoma cellsto lung sections.In vivo: inhibition of lung metastasis and the melanoma cell adhesion to vascular lung endothelium." (PMID 36986905, 2023). "Collectively, these results confirm that the ability of PTP 9 to sensitize cancer cells to the effects of IFNγ and TNFα are not restricted to melanoma cells but extend to other solid tumors, many of which exhibit resistance to ICI therapy." (PMID 36968224, 2023). "IFN-γ upregulation in the TME of mice bearing SC melanoma and treated with guadecitabine/ICBs may stimulate TAM-M1 polarization, that can be further sustained by the up regulation of IFN-γ and TNF-α systemic levels." (PMID 36934257, 2023). "Moreover, ongoing phase III clinical trials (NCT00001296) investigating the combination of TNF‐α and IFN‐γ with hyperthermia isolated limb perfusion (HILP) in patients with locally advanced melanoma hold promise for achieving positive outcomes." (PMID 38069556, 2023). "S100A4 not only activates the nuclear factor‐kappa B (NF‐κB) pathway and leads to the release of the tumor necrosis factor (TNF)‐α, but also shapes an inflamed TME by inducing the secretion of IL‐8 and C—C chemokine ligand 2 (CCL2), playing an oncogenic role in malignant melanoma." (PMID 37414584, 2023). "Then, these EVs tended to induce a proinflammatory activation of macrophages by increasing the expression of COX-2 and the release of inflammatory cytokines, such as IL-1β, IL-6, TNF-α, and NO, so as to establish an inflammatory TME which in turn facilitated the progression of melanoma." (PMID 37575250, 2023). "In this sense, the combination of TNF-α and secondary mitochondria-derived activator of caspases (SMAC) mimetics has been reported to induce immunogenic cell death in fibrosarcoma, melanoma, liposarcoma, synovial sarcoma and patient-derived cutaneous squamous cell carcinoma." (PMID 38077402, 2023). "In the co-culture assays, we evaluated the potential of melanoma patient B cells to mediate modulation of autologous CD4+ T-helper cell phenotype and functions, including the modulation of T cell proliferation, TNF-α, IFN-γ, and FOXP3 expression and induction of FOXP3+ Tregs." (PMID 35909944, 2022). "Clinical data have shown that the administration of anti TNF-α monoclonal antibodies due to immune related adverse events in immunotherapy treated melanoma patients did not compromise treatment outcomes." (PMID 35743911, 2022). "Differential transcriptomic analysis of high and intermediate metastatic (HIM-) melanoma compared to low metastatic (LM-) melanoma showed the most marked differences in pathways involved in cell migration, angiogenesis, EMT, oxidative phosphorylation or TNF-α signaling." (PMID 35109875, 2022). "In melanoma, pharmacological inhibition of PI3K has been shown to subdue TNF-driven sphere formation abilities from the cells, suggesting that PI3K/AKT signaling might mediate the inhibition of melanoma differentiation induced by pro-inflammatory pathways." (PMID 36434616, 2022). "Targeting activated JAK1/2 with Ruxo selectively suppresses IFNγR1KO but not scrambled control melanomas, coupled with enhanced effector functions (e.g., TNF production) and reduced Treg frequency in TILs." (PMID 36008408, 2022). "Therefore, when palpable melanoma tumors were injected with a combination of TNFα, CD40L, and an antibody against the melanoma antigen TRP1, tumors were almost completely eradicated in all mice." (PMID 36124553, 2022). "However, whereas the effect of TNF in BN soft tissue sarcoma was realized after three administrations, the increased accumulation in the B16BL6 melanoma was already observed within 12 h of the first treatment." (PMID 36297598, 2022).
melanoma (continued). "Additionally, we have previously showed that the melanoma-derived lysate TRIMEL induces the release of Th1-polarizing and pro-inflammatory cytokines such as IL-6, TNF-α, and IL-12 in therapeutically used monocyte-derived DCs." (PMID 35805888, 2022). "Furthermore, experiments on melanoma cells have demonstrated that NK cells directly contact with tumor cells and release IFN-γ and tumor necrosis factor (TNF-α), thereby inducing EMT of tumor cells." (PMID 36611857, 2022). "Functional assay using the melanoma mouse model and the human melanoma tissues revealed that NKTR-214 expands, maintaining effector CD8+ T cells and depleting Tregs by effector CD8+ T cell-derived IFN-γ and TNF-α." (PMID 35432377, 2022). "Further study indicated that reduction of TNF-α is associated with hsa-miR-181 family, hsa-miR-122, hsa-miR-149, hsa-miR-498, and hsa-miR-3187-3p enriched in melanoma-derived exosomes, especially hsa-miR-181 family and hsa-miR-498 interact directly with the 3′-UTR sequence of TNF-α." (PMID 36612077, 2022). "CTLs bind to melanoma cells via TAA presented on MHC molecules and then exert an antitumor effect on melanoma cells by releasing perforin and granzyme B to induce apoptosis and secreting cytokines such as IFN-γ and TNF to reinforce the inflammatory TME." (PMID 36003368, 2022). "However, TNF-α+ CD20+ TIL-B were evident in human melanoma lesions by IHC/IF cytokine co-staining, and their presence was confirmed in an independent melanoma tissue cohort by scRNA-seq analyses." (PMID 35909944, 2022). "In addition, TNF-α administration fostered the infiltration of CD8+ T cells into tumor tissues and repressed melanoma growth in dysbiotic mice by increasing the expression level of ICAM-1 in the tumor vasculature." (PMID 36726985, 2022). "Recently, the overexpression of TNF, IFNG and IL2, among other molecules, have been reported as key molecules that may enhance melanoma progression through activating the JAK–STAT signaling pathway." (PMID 36289681, 2022). "In melanoma cells, the activation of AHR promotes TNFα-dependent inflammation and metastasis." (PMID 36292946, 2022). "IL‐12 is known to stimulate production of TNF‐α by T cells and NK cells and combinations of IL‐12 and TNF‐α have been shown to induce CD8+ T cell and NK cell‐dependent antitumor immune responses in murine models of melanoma and sarcoma." (PMID 35790025, 2022). "Our work reports the impact of TNFα on cancer cells of different origin – non-epithelial malignant melanoma cells of neural crest origin and colorectal carcinoma cell lines of epithelial origin." (PMID 33957885, 2021). "Melanoma TAMs were also characterized in situ by their high content of CCL20, TNF, and VEGFA by multicolor immunofluorescence in cryopreserved samples; we now show that this particular cytokine profile may be detected and quantified in diagnostic FFPE." (PMID 34439098, 2021). "The immune suppressive effects of TNFα have led to the TICIMEL phase 1b clinical trial evaluating the activity and safety of combination anti-TNFα and immune checkpoint inhibitors (anti-PD1 and anti-CTLA4) in advanced melanoma (NCT03293784)." (PMID 34073253, 2021). "TNFα induces BRN2 signaling and, in line with often mutually exclusive expression of BRN2 and MITF, it has been identified as an inhibitor of MITF and Melan A in 40 different melanoma cell lines." (PMID 34604096, 2021). "The TNFα-mediated induction of antigen presenting molecules was weak and/or uncommon; HLA-ABC showed a mean fold induction of only 1.9, while HLA-DR was induced in only 12.5% of melanoma cells, suggesting it to be a poor effector of tumor recognition." (PMID 34073253, 2021).
melanoma (continued). "Nevertheless, we found that the level of TNF in the serum of BLM-treated melanoma-bearing mice was increased (data not shown)." (PMID 34378880, 2021). "Interleukin-1-α (IL-1α) and interleukin-1-β (IL-1β) upregulate MC1R mRNA in normal human melanocytes, while TNF-α and TGF-β, that potently repress melanogenesis in melanoma cells, moderately downregulate MC1R expression in normal melanocytes and mouse melanoma cells." (PMID 34356109, 2021). "In addition, TNF-α was previously used with good efficacy in patients with limb soft tissue sarcomas (STS) and in-transit melanoma by targeting the hap-hazard neovascular growth within the TME of these lesions." (PMID 33986746, 2021). "For example, some trials of isolated limb perfusion with TNF in melanoma patients did not demonstrate a significant improvement in the TNF-treated group, whereas others reported some positive effects." (PMID 33917839, 2021). "However, there were differences in the cytokine profile up-regulated regarding the MP polarization profile; MP-GM/melanoma produced more TNF and CCL20, whereas MP-M/melanoma produced more VEGFA." (PMID 34439098, 2021). "MSCs intravenously injected 24 h after melanoma induction significantly enhanced the cytotoxicity of CD8+ CTLs and NK cells, increased the production of anti-tumorigenic cytokines (TNF-α, IFN-γ, IL-17) in tumor-infiltrated CD4+ Th1 and Th17 lymphocytes and attenuated melanoma growth and progression." (PMID 34830312, 2021). "We found that IFNβ strongly upregulated the levels of both Gal-9 protein and mRNA in A375 human melanoma cells, whereas IFNγ only moderately induced Gal-9 and TNFα did not have a detectable effect." (PMID 33547304, 2021). "Based on these results, it was postulated that TNFα and IL-1β secreted by keratinocytes could be involved in an RGP/VGP melanoma phase switch." (PMID 33430277, 2021). "TNFα can also promote tumor cell dissemination by increasing angiotropism, the process whereby melanoma cells around blood vessels leads to metastasis without entry into the blood circulation." (PMID 34604096, 2021). "In melanoma, TNFα induces cell invasion and aggressiveness, extravascular migration of cancer cells and impairs CD8 T lymphocytes accumulation in the TME, moreover blocking TNFα prevents metastasis formation in the lungs in pre-clinical models." (PMID 33540543, 2021). "Moreover, regulatory T-cells, which are generally considered a bad prognostic factor in melanoma, can strongly express TNFR2 on their surface, are the most potent Tregs and can survive longer than the others in the presence of TNFα." (PMID 34604096, 2021). "Although we did not perform statistical analyses on the three transitory melanoma cell lines, TNFα clearly reduced both MITF and Melan A levels and concurrently increased NGFR and AXL expression in this melanoma subtype." (PMID 34073253, 2021). "The upregulation of AXL occurred predominantly in the transitory and dedifferentiated melanomas, suggesting that although MITF and AXL expression has been reported to be inversely correlated in melanoma, their regulation by TNFα appear dependent on variable mediators." (PMID 34073253, 2021). "This reprogramming results in elevated production of effector molecules such as CD25, IFN-γ and TNF-α, and significantly enhances the anti-tumor activity of antigen-specific CTLs and ROR1-targeting CAR T cells in syngeneic murine melanoma and pancreatic cancer models." (PMID 34210970, 2021). "This was particularly interesting as, in our hands, long-term cultures of dedifferentiated melanoma cells derived from patient biopsies remain dedifferentiated in the absence of exogenous TNFα (data not shown)." (PMID 34073253, 2021). "Furthermore, we demonstrate that TNFα is a poor inducer of antigen presentation molecules HLA-ABC and HLA-DR in melanoma cells." (PMID 34073253, 2021).
melanoma (continued). "It is also important to note that no single melanoma cell line showed the TNFα-mediated induction of all four immune markers, further highlighting the variability in TNFα downstream signaling." (PMID 34073253, 2021). "We show that primary human T cells adhere to endothelial vessel walls upon perfusion of microvessels and can be stimulated to undergo transendothelial migration (TEM) by TNFα-mediated vascular inflammation and the presence of CXCL12 gradients or ECM-embedded melanoma cells." (PMID 34361000, 2021). "Our in vitro study of direct TNFα influence demonstrates two distinct outcomes in tumor cells of different origin, in non-epithelial malignant melanoma cells of neural crest origin, and in colorectal carcinoma cells derived from the epithelium." (PMID 33957885, 2021). "This difference with respect to regressing melanoma was attributed to the different cytokine microenvironment; in fact, fibrogenic cytokines such as IL-6, TGF-β, TNF-α, bFGF and PDGF are expressed by melanoma while TNF-α, an antifibrogenic cytokine, was found to be more expressed in the halo nevus." (PMID 34300213, 2021). "Similarly, we now observed up-regulation of TNF and VEGFA mRNA expression by melanoma-conditioned MP-GM(BLM) and, to a lesser amount, by MP-M(BLM), which were separated from BLM melanoma cells after co-culture." (PMID 34439098, 2021). "Importantly, cells cultured with anti-TNF-α neutralizing antibody saw a significant restoration in viability, suggesting that TNF-α production from ILC2 has a direct effect on melanoma apoptosis." (PMID 34531874, 2021). "Within this context, we observed a trend to increased TNF-α, IFN-α-2a and IFN-λ1 secretion as well as an increased expression of CD80, PD-L1 and HLA-ABC by the BDCA-1+/BDCA-3+ myDC after treatment with supernatant from T-VEC treated melanoma cells." (PMID 34777344, 2021). "In melanoma cells, TGF-β1 can induce cell death, while TNF-α can reduce the relative cell death number, a phenomenon that may be associated with both regulating Twist1 protein levels." (PMID 35069596, 2021). "Exogenous TNFα did not consistently induce the expression of PD-L1 (only 3/40 melanoma cell lines, A2058, C086 and Mel270, showed >1.5 fold induction in response to TNFα)." (PMID 34073253, 2021). "Since IL6 increases melanoma invasiveness and elevated levels of IL6 are linked with worse prognosis in non-responding patients, resulting effect of TNFα overexpression can be also adverse." (PMID 33957885, 2021). "These include C-reactive protein (CRP), interleukins (IL)-1, -6, and -8, IL-1 receptor antagonist (IL-1Ra), soluble IL-6 receptor (sIL-6R), tumor necrosis factor-alpha (TNF-α), a chemokine promoting macrophage migration, chemokine C-C motif ligand 3 (CCL3), and melanoma inhibitory activity (MIA)." (PMID 34441422, 2021). "Fourth, melanoma cell-derived exosomal PD-L1 inhibits cytokine production and cytotoxicity of CD8+ T cells by decreasing the expression of GzmB and inhibiting the production of interleukin-2 (IL-2) and tumor necrosis factor (TNF)." (PMID 32322256, 2020). "The expression of TNFα in an inflamed TME positively correlates with the expression of PD-L1 and TIM-3, along with impaired accumulation and increased activation-induced death of CD8+ TILs in melanoma models treated with anti-PD1 therapy." (PMID 33194652, 2020). "In a study on melanoma cells, the inflammatory cytokines interleukin 1α (IL-1α) and TNFα, secreted by melanoma cells, but no other cytokines, were reported to stimulate the phosphorylation, and subsequent ubiquitination and degradation of IFNAR1." (PMID 32604862, 2020). "Particularly, in melanoma, tumor growth was impaired in TNF KO and TNFR1 KO but not in TNFR2 KO mice injected with B16K1 cells, a genetically-modified cell line derived from B16F10 cells, which stably express the MHC-I molecule H-2Kb." (PMID 33202705, 2020). "Stimulation with IFNy or TNFα over 72 h showed no influence on H3K27me3 expression in melanoma cells by IHC." (PMID 32041674, 2020).
melanoma (continued). "Recently, TNF-α and IL-6 have also been found as regulators of PD-L1 in a variety of cells, however, whether they can regulate PD-L1 expression in HCC or melanoma is unknown." (PMID 32477009, 2020). "However, it was not the scenario that emerged in the majority of cancer cells, because they lost sensitivity to TNFα secreted by CD8+ T lymphocytes and NK cells in melanoma." (PMID 32391269, 2020). "One of these products, L19-IL2 is currently being evaluated in phase II clinical trials as single immunostimulatory agent [NCT02957019] and phase III in combination with targeted TNF for the of patients with fully resectable stage IIIB, C melanoma [NCT02938299]." (PMID 33110477, 2020). "Melanoma and non-melanoma skin cancers have been linked to IBD treatment, including thiopurines and anti-TNF agents." (PMID 32842528, 2020). "We also assessed expression of activation-responsive immune genes TNF, IL21, IL10, IL13, and CFS2 in the ICB melanoma dataset, and found that IFNG, TNF, and interleukins IL21 and IL10 seemed to increase upon treatment in responders, even though they were not differentially expressed." (PMID 32471032, 2020). "The present study, for the first time, demonstrated that TNF-α and IL-6 secreted by adipocytes could upregulate PD-L1 level in HCC and melanoma." (PMID 32477009, 2020). "Interestingly, inflammatory cytokines including IL-6, IL-10, IL-12p70, IFN-γ, TNF-α, MCP-1 and KC were previously shown to be differentially expressed in male and female C57 BL/6J mice in the melanoma model." (PMID 33287312, 2020). "Melanoma-derived exosomes decrease TNFα secretion in CD8+ cells and are enriched for hsa-miR-181a, which is capable of interacting directly with the 3′-UTR sequence of TNFα and driving immune escape in melanoma." (PMID 32992819, 2020). "In melanoma samples from ICER-deficient mice, an enhanced pro-inflammatory, M1-like polarization (high iNOS and TNF-α expression) was detected, with no variation in the total number of tumor-infiltrating macrophages." (PMID 33212945, 2020). "In addition, tumor-associated macrophages secrete several cancer-stimulating molecules, such as IL-1, TNF-α, IFN-γ, angiotensin, COX-2, and IL-1β, to support the growth, angiogenesis, and metastasis of melanoma." (PMID 33171792, 2020). "In order to increase circulating half-life and decrease immunogenicity, an alternative cytokine treatment with TNF-α administered in a polyethylene glycol (PEG) was trialled in dogs with different tumours, including melanoma, although only a minor/transient antitumor response was demonstrated." (PMID 30987001, 2019). "Building on our preclinical findings, we initiated at Toulouse Oncopole a phase 1b clinical trial (TICIMEL -NCT03293784) in 30 advanced melanoma patients to investigate the concomitant administration of Ipilimumab (anti-CTLA-4), Nivolumab (anti-PD-1) and anti-TNF (Infliximab or Certolizumab)." (PMID 31727152, 2019). "As control, the release of TNFα, IL-6, and IFNγ was also determined for the untreated melanoma cells alone (data not shown)." (PMID 31192129, 2019). "Notably, ubiquitination of endogenous BRAF was induced by TNFα or IL-1β treatment in both melanocytes and melanoma cells, while depletion of ITCH abrogated TNFα-stimulated BRAF ubiquitination." (PMID 31015455, 2019). "Similarly, a pH of 6.5 resulted in a declined responsiveness of tumor infiltrating T cells from melanoma patients, with decreased expression of TCR components (such as CD3ζ chain) and impaired secretion of IL-2, tumor necrosis factor-α (TNF-α), and IFN-γ." (PMID 31881671, 2019). "In SK-MEL-28, the phosphorylation level of IKKα/β without TNFα treatment was high and elevation of the phosphorylation level with TNFα treatment was not clear compared with other melanoma cell lines." (PMID 31611597, 2019).